ENSG00000238854
Synonyms: LOC124900270
Gene: Small nucleolar RNA gene on chromosome 8 (141,447,475 to 141,447,549, forward strand). Ensembl gene ENSG00000238854.
Gene Ontology:
Biological process: RNA processing
Cellular component: nucleolus
Homologues: Orthologues: rat Snord5 (81% identical), mouse Gm24299 (77% identical). Paralogues in human: SNORD5 (85% identical).